GPR15 (G protein-coupled receptor 15)
Diseases named in the same sentence as GPR15 in open-access papers (continued):
Sharing a sentence is not in itself a finding about the gene and the disease.
tumor (continued). "Interestingly, in a more recent study testing the potential anti-tumor effect of rTM, it was suggested that GPR15 mediates rTM-induced growth inhibition of pancreatic ductal adenocarcinoma (PDAC)." (PMID 37457732, 2023). "Whether GPR15 has a role in spatial distribution of effector cells within tumor regions to establish unique, intratumoral immune niches is currently not known and warrants future investigation." (PMID 38074634, 2023). "Thus, GPR15 represents a promising novel target for modifying T cell-mediated anti-tumor immunity in CRC." (PMID 37457732, 2023). "The finding that C10orf99 suppresses proliferation in tumor cells via SUSD2 led to the hypothesis that similar effects could be evoked via GPR15 in cancer." (PMID 34639163, 2021). "Apart from GPR15, however, C10orf99 may act as a tumor suppressor by suppressing proliferation of several tumor cell lines via G1 arrest by interacting with another binding receptor, called sushi domain containing 2 (SUSD2)." (PMID 34639163, 2021). "Moreover, the immune infiltrates in the colon polyps of Gpr15-KO mice as well as the human CRC tumor samples with reduced GPR15 expression showed significant increases in the population of pro-inflammatory immune cells such as IL-17+ CD4+ and IL-17+ CD8+ T cells." (PMID 38074634, 2023). "Intriguingly, we noted reduced GPR15 expression on tumor infiltrating CD4+ and CD8+ T cells in GPR15L-treated Gpr15-Het mice compared to the PBS-treated Gpr15-Het mice." (PMID 38074634, 2023). "The anti-tumor effect of rTM was only observed in PDACs with high GPR15 expression, and rTM suppressed NF-kB and ERK1/2 activation in a GPR15-dependent manner." (PMID 37457732, 2023). "In human study, immune cells were isolated from tumor tissues and healthy surgical tumor margins (STM), and their proportions as well as expression of GPR15 was analyzed by flow cytometry." (PMID 38074634, 2023). "In agreement with observations in our patient cohort, we observed reduced GPR15 as well as GPR15L expression in the tumor compared to tumor border and normal tissue adjacent to tumor border." (PMID 38074634, 2023). "To delineate GPR15-mediated immune mechanisms involved in tumor suppression in the AOM-DSS CAC disease model, we analyzed the immune cells recovered from the colon in Gpr15-Het and Gpr15-KO mice at week 10, post AOM-DSS treatment by flow cytometry." (PMID 38074634, 2023). "Consistent with a protective role of GPR15, administration of GPR15L to established tumors in the MC38-CRC mouse model resulted in a significant reduction in tumor burden and increased survival." (PMID 38074634, 2023). "Consistent with a protective role of GPR15, administration of GPR15L to established tumors in the MC38-CRC model increased CD45+ cell infiltration, enhanced TNFa expression on CD4+ and CD8+ T cells at the tumor site and dramatically reduced tumor burden." (PMID 38074634, 2023). "We thus hypothesized that the high expression of GPR15 in COAD can contribute to the homing and infiltration of FOXP3+ regulatory T cells (Tregs), which in turn boost the immunity response of the tumor and results in a better prognosis." (PMID 31835584, 2019). "Thus, there might be differences in GPR15-dependent infiltration of effector CD4+ and CD8+ T cells depending on the tumor location and subsequent changes in the TME (subcutaneous versus colon)." (PMID 38074634, 2023). "Putative GPR15 co-expressed genes, such as TACR1, TAS2R9, SPDYE4, or GPR182, could be a more specific sign for tumor cells of adenocarcinoma or for healthy epithelial cells from which the tumor originates since all four genes were not expressed in GPR15+CD3+ lymphocytes." (PMID 34639163, 2021). "While this suggests that GPR15 may play a differential role in non-immune cells, such as cancer cells, it needs to be tested in vivo to understand the impact of GPR15 expression in various cell types in the tumor microenvironment." (PMID 38074634, 2023).
tumor (continued). "Similar to mice, the frequency of GPR15+ Tregs, but not that of GPR15+ Teffs, in the tumor sites of patients with CRC was significantly higher than that in non-tumor sites, suggesting a distinct role for GPR15 in Treg delivery to CRC sites in humans." (PMID 37457732, 2023). "To ascertain tumor-specific changes in the immune environment, we performed a comprehensive assessment of immune cell phenotypes and their functional state in large intestine lesions with polyps/tumors (LIP) and without polyps (LI) of AOM-DSS treated Gpr15-Het and Gpr15-KO mice." (PMID 38074634, 2023).
cancer (7 papers, 2018 to 2025). A tumor composed of atypical neoplastic, often pleomorphic cells that invade other tissues. "In the RUNX3→GPR15 case, we adopted dysregulation relationship between RUNX3 and GPR15 to confirm the anti-cancer function of RUNX3 in CRC." (PMID 32717065, 2020). "Still, in TCGA CRC dataset, the expression of GPR15 significantly decreases in cancer and is significantly correlated with good prognosis (HR = 0.735, 95% CI: 0.621‒0.870)." (PMID 32717065, 2020). "For RUNX3→GPR15, the regulatory intensity was reduced from normal to cancer with the intensity value being 0.441 (normal) and −0.010 (cancer), and the expression level of the target, GPR15, significantly decreased as shown." (PMID 32717065, 2020). "Recently, GPR15 was deorphanized and its corresponding natural ligand demonstrated an ability to inhibit cancer cell growth." (PMID 31835584, 2019). "The expression levels of GPR15 were evaluated in 33 different cancers using the data from the Cancer Genome Atlas (TCGA) and the Genotype-Tissue Expression (GTEx) databases." (PMID 31835584, 2019). "In this study, we firstly performed pan-cancer analysis to elucidate the potential role of GPR15 in cancers." (PMID 31835584, 2019). "We provide evidence that GPR15 acts as an immunomodulator and can be considered as a novel target for immunotherapy for the four cancers." (PMID 31835584, 2019). "To dissect the effects of the expression of GPR15 in a genome-wide manner, we performed differential gene expression (DEG) analysis on the GPR15 low-expression group compared to the GPR15 high-expression group in the four cancer types." (PMID 31835584, 2019). "Our study provides novel insights into the role of GPR15 in a pan-cancer manner and discovered a potential hit compound for GPR15 antagonists." (PMID 31835584, 2019). "Together, the results of the enrichment analysis revealed that the regulatory role of GPR15 in the four cancers is strongly correlated to immunity function." (PMID 31835584, 2019). "Our study identified a number of common genes that are in the GPR15 regulatory network in four cancers." (PMID 31835584, 2019). "Among all of the 33 cancer types from the TCGA database, cancers with significant differential GPR15 expression (on the basis of difference of median expression between cancer samples and paired normal samples) are COAD (downregulated, p = 3.06 × 10−12) and READ (downregulated, p = 6.80 × 10−4)." (PMID 31835584, 2019). "The G protein-coupled receptor 15 has also been shown to be involved in angiogenesis and inflammation, which indicated a role of GPR15 in smoking-associated diseases such as cardiovascular diseases and cancer." (PMID 30127295, 2018). "This study also revealed that commonly upregulated gene sets in the high GPR15 expression group (stratified via median) of COAD, HNSC, LUAD, and STAD are enriched in immune systems, indicating that GPR15 might be considered as a potential target for cancer immunotherapy." (PMID 31835584, 2019). "According to gene dysregulation analysis, the regulatory intensity of RUNX3→GPR15 is decreased from normal to cancer, which suggests that RUNX3 at least partly contributes to the high expression of GPR15 in normal." (PMID 32717065, 2020). "As for T cells, for three types of cancer, excluding COAD, the GPR15 expression value was significantly positively correlated with CD8+ T cell infiltration." (PMID 31835584, 2019). "Next, we added NuRD complex as a new molecule and ran the “Path Explorer” tool between SET A (NuRD) and SET B (SF3B1B, PHF6, EIF4G3, DCP2, GPR15, miR-490, LINC01222, LINC01718, LINC02036) with the same parameters for diseases: “Cancer”, “Infectious Disease”, and “Reproductive Disease System”." (PMID 38790189, 2024).
cancer (continued). "However, no study reported the potential role of GPR15 in a pan-cancer manner." (PMID 31835584, 2019).
cardiovascular diseases (4 papers, 2018 to 2025). "Using a translational approach, our data provide evidence that GPR15 is linked to cardiovascular diseases, mediating the adverse effects of smoking." (PMID 36613626, 2022). "Smoking is a major risk factor for cardiovascular diseases and has been implicated in the regulation of the G protein-coupled receptor 15 (GPR15) by affecting CpG methylation." (PMID 30127295, 2018). "These smoking-related changes in GPR15 methylation and expression could perturb immune function and increase the risk for complex diseases with inflammatory pathogenesis, which could contribute to cardiovascular disease." (PMID 30127295, 2018). "Current studies have demonstrated that increased expression of GPR15 is associated with cardiovascular disorders, mediating the negative consequences of smoking." (PMID 37762221, 2023).
inflammation (3 papers, 2015 to 2025). Aberrant reaction of the microcirculation characterized by movement of fluid and leukocytes from the blood into extravascular tissues. "Compared with those in Gpr15+/+ mice, DSS treatment resulted in milder colonic inflammation in Tg(hGPR15) mice, characterized by less weight loss, lower DAI scores, minimal colon shortening, and reduced histopathological and endoscopic scores." (PMID 40957881, 2025). "As we showed in a previous study, this very minor methylation change, identified in whole blood DNA samples, is related to the expansion of a small subset of GPR15 expressing T cells potentially involved in lung inflammation." (PMID 27013061, 2016). "If GPR15+ T cells are activated and expanded as a consequence of lung inflammation and if the occurrence of this cell population in peripheral blood might reflect the degree of already established lung inflammation, it remains elusive." (PMID 27493699, 2015).
immune diseases (1 paper, 2023). "Therefore, ligand-independent endocytosis of GPR15 provides a basis for developing interventions targeting this receptor in human inflammatory/immune diseases, where GPR15-expressing cells may play pathogenic roles." (PMID 37457732, 2023). "Over the past decade, a growing number of studies have indicated the involvement of GPR15 and its ligands in a variety of human immune disorders, making them promising therapeutic targets." (PMID 37457732, 2023). "Since the discovery of its novel function as a colon-homing receptor of T cells in mice a decade ago, GPR15 has been rapidly gaining attention for its involvement in a variety of inflammatory and immune disorders." (PMID 37457732, 2023).
GPR15 also shares sentences with these, for which no sentence is quoted: multiple sclerosis (3 papers); colonic polyps (2); Obesity (2); adenocarcinoma (1); atopic dermatitis (1); bullous pemphigoid (1); cervical (1); chronic obstructive pulmonary disease (1); Crohn disease (1); diabetes (1); endothelial dysfunction (1); hematopoietic cancers (1); Hypertension (1); infarction (1); infectious disease (1); interstitial lung disease (1); ischemic stroke (1); lichen planus (1); pneumonia (1); rectal adenocarcinoma (1); Reproductive Disease (1); Stroke (1).